TERT (telomerase reverse transcriptase)
Diseases named in the same sentence as TERT in open-access papers (continued):
Sharing a sentence is not in itself a finding about the gene and the disease.
glioma (continued). "Two mutually exclusive mutations play a role in telomere maintenance in gliomas: telomerase reverse transcriptase (TERT) mutations in hot spot promoter regions C228T, C250T result in increased expression of telomerase." (PMID 25943885, 2015). "Previously, we evaluated the frequency, distribution, and prognostic significance of TERT promoter mutations when combined with IDH mutations in WHO grade II to IV gliomas." (PMID 26314843, 2015). "The distribution of TERT promoter mutations in different glial tumors followed the reported pattern with highest frequencies being present in primary glioblastomas, followed by oligodendrogliomas, oligoastrocytomas and astrocytomas." (PMID 25797251, 2015). "The discovery of mutations in the TERT promoter and subsequent reports of their occurrence at a high frequency in gliomas has resulted in further refinement of glioma classification." (PMID 25797251, 2015). "RNA was available from 111 gliomas, of which 88 carried TERT promoter mutations (–124C > T n = 67; –146C > T n = 21) and 23 were without the mutations." (PMID 25797251, 2015). "In glioma genomics, TERT promoter mutations are frequently found in over 70% of primary GBM and oligodendrogliomas, and less frequently in oligoastrocytomas and WHO grade II and III diffuse astrocytomas." (PMID 26314843, 2015). "The rs2853676 polymorphism has been mapped to intron 2 of the TERT gene, which was implicated in an increased risk of glioma in 2009." (PMID 26042809, 2015). "Our single-locus analyses show an association between inherited variation in the telomerase component genes TERC and TERT and glioma risk, as previously reported." (PMID 26646793, 2015). "Analysis of quantitative real-time PCR data showed statistically significant higher levels of mRNA in gliomas with TERT promoter mutations than in wildtype tumors (P < 0.0001, t-test)." (PMID 25797251, 2015). "Of interest to glioma genomics, TERT promoter mutations occur in 70-80% of primary GBMs and >70% of oligodendrogliomas, but occur less frequently in both lower grade astrocytomas and most oligoastrocytomas." (PMID 24722048, 2014). "The results of the present study demonstrate that mutations in the TERT gene promoter are associated with decreased survival in glioma patients." (PMID 24937153, 2014). "TERT promoter mutations were detected in 101 glioma samples (grades I–IV) and 49 other brain tumors by sequencing." (PMID 24937153, 2014). "As observed, within Grade III and IV gliomas separately, tumors with mutations in both TERT and IDH1/2 had the best median OS (oligodendroglioma signature), followed by those with an IDH1/2 mutation only (Grade II-III astrocytoma and secondary GBM signature)." (PMID 24722048, 2014). "It is well-established that hypoxia usually occurred with glioma progression, and the present study found that high levels of TERT gene transcription were maintained from the mutated promoter during hypoxia." (PMID 24937153, 2014). "Four distinct subgroups of Grade III gliomas were identified when stratified by the combination of the TERT promoter and IDH1/2 mutation status (log-rank p=0.0008)." (PMID 24722048, 2014). "The discovery of TERT promoter mutations in these subsets of gliomas creates an opportunity for genomics to supplement histopathological analysis, especially when combined with IDH1/2 mutation status." (PMID 24722048, 2014). "In this study, the effect of TERT promoter mutations was examined in glioma cells, and the mutation status of the promoter was analyzed in glioma patients with respect to glioma progression and patient survival." (PMID 24937153, 2014). "During preparation of this manuscript, several papers emerged reporting identification of somatic and germline mutations in the TERT promoter in a range of tumour types and cell lines including melanoma, glioma, hepatocellular carcinoma and others." (PMID 24550717, 2014).
glioma (continued). "Our analysis of this tumor cohort expands upon previous reports identifying frequent TERT promoter mutations in gliomas, examines the association between TERT promoter and IDH1/2 mutations in glioma, and assesses their joint influence on OS." (PMID 24722048, 2014). "In the multivariate Cox model adjusted for potential risk factors, TERT promoter mutations were associated with a significant increase in overall mortality for grade II gliomas (HR 3.058; 95% CI: 1.886 to 4.958; P<0.001)." (PMID 24937153, 2014). "To assess the prevalence and prognostic impact of TERT promoter mutations we sequenced the proximal TERT promoter hotspot mutations (C228T and C250T) in 473 adult gliomas." (PMID 24722048, 2014). "Utilizing a combined analysis of IDH1/2 and TERT promoter mutations in adult glioma, we have derived a greatly expedited and simplified genetic signature of three common glioma subtypes, namely Grade II-III astrocytomas, oligodendrogliomas, and GBMs." (PMID 24722048, 2014). "Here, we have assessed the characteristic variance between IDH1/2 and TERT promoter mutations among several glioma subtypes that help refine the diagnosis of gliomas." (PMID 24722048, 2014). "Hazard ratios from survival analysis of glioma patients were determined relative to the presence of TERT promoter mutations." (PMID 24937153, 2014). "We analyzed the relationship between overall survival (OS) and the presence of IDH1/2 and TERT promoter mutations in a panel of 473 adult gliomas." (PMID 24722048, 2014). "As these gliomas, wildtype for both TERT promoter and IDH1/2 mutations, represented a clinically distinct unit further investigation is required to delineate critical driver mutations in this subset of gliomas." (PMID 24722048, 2014). "The presence of mutations −124 C>T and −146 C>T was associated with increased expression of TERT mRNA in gliomas." (PMID 24937153, 2014). "Patients whose Grade III-IV gliomas exhibit TERT promoter mutations alone predominately have primary GBMs associated with poor median OS (11.5 months)." (PMID 24722048, 2014). "Among the 112 Grade II gliomas, 103 were characterized by either mutations in both TERT and IDH or IDH alone." (PMID 24722048, 2014). "Specific data for the TERT rs2736100 polymorphism were stratified by cancer type: the lung cancer subgroup, the glioma subgroup and the other cancers subgroup." (PMID 22221621, 2012). "Higher-grade glioma tissues were seen to have more TERT mutations than low-grade glioma." (PMID 40564017, 2025). "In most tumors, including gliomas, TERT expression is associated with poor prognosis." (PMID 40149633, 2025). "Additionally, our analysis of glioma transcriptomic data from the TCGA database revealed that gliomas with TERT promoter mutations exhibit higher expression levels of SLC7A5." (PMID 40149633, 2025). "Moreover, the proportions of IDH1 and TERT promoter mutations were higher in neocortical gliomas than in mesocortical gliomas (67.9% vs. 31.6%, p < 0.01 and 68.4% vs. 25.0%, p < 0.001, respectively)." (PMID 40149633, 2025). "TERT mutations might occur in gliomas and papillary thyroid carcinoma, two entities that rarely metastasize into the liver." (PMID 40426891, 2025). "Notably, within IDH‐mt glioma cases, TERT promoter mutations were detected in all oligodendrogliomas but only in 4.55% of astrocytomas, consistent with the descriptions provided in the WHO CNS guidelines and supported by previous studies." (PMID 39804195, 2025). "Since LAT1 is the protein encoded by the SLC7A5 gene, we hypothesize that the higher TERT promoter mutation rate in neocortical gliomas may lead to increased LAT1 expression, which in turn enhances FET uptake and consequently increases metabolic activity." (PMID 40149633, 2025).
glioma (continued). "Moreover, neocortical WHO grade 3 gliomas exhibited higher rates of TERT promoter mutation and 1p/19q co-deletion (TERT promoter-mutant: 66.7% vs. 12.5%, p < 0.05; 1p/19q-codeleted: 66.7% vs. 12.5%, p < 0.05)." (PMID 40149633, 2025). "Notably, ZNF148 has been suggested as a potential regulator of TERT, which is associated with the prognosis of glioma patients." (PMID 41007824, 2025). "Notably, in low-grade gliomas, the combination of chromosome +7/-10 with TERT mutation or EGFR amplification is considered an independent molecular marker of the worst clinical outcome." (PMID 41201287, 2025). "Furthermore, the entropy of T1CE was found to be crucial for differentiating the TERT mutation status in glioma patients." (PMID 39131044, 2024). "Diffuse gliomas with mutations of the promoter region of TERT (TERT-p) have ambivalent prognoses." (PMID 38893240, 2024). "Three feature selection methods and six classification algorithms were employed to investigate whether preoperative multi-parameter MRI can differentiate TERT promoter mutation status in gliomas." (PMID 39131044, 2024). "Using a combination of different feature selectors and classification algorithms may help predict glioma TERT promoter mutation status." (PMID 39131044, 2024). "Since TERT mutation is an unfavorable factor in IDHwt tumors, once a patient with glioma is predicted to be IDHwt-TERTmut, it may demand sufficient attention from physicians and impose additional psychological and testing expense burden on the patient." (PMID 38982347, 2024). "The complex interplay between cell transformation, the tumor microenvironment, and inflammation, particularly neutrophil infiltration related to TERT mutations, may underlie the challenging prognosis of IDHwt gliomas." (PMID 38982347, 2024). "We found that contrast-enhanced T1-weighted imaging (T1CE) was the most important parameter in predicting the model and among the radiomic features in this study, the entropy of T1CE contributed the most to distinguishing between TERT mutated and TERT wild-type gliomas." (PMID 39131044, 2024). "The prognostic role of TERT-p mutation in gliomas seems to be ambivalent." (PMID 37570630, 2023). "Another commonly mutated gene region in glioma is the promotor of the TERT gene." (PMID 36776000, 2023). "IDH1/2 gene and TERT promoter mutations are more frequent in patients with glioma." (PMID 37250582, 2023). "Meanwhile, in our previous study, the results showed that the GLCM texture features from ADC maps played an important role in predicting IDH mutation and TERT promoter mutation of gliomas, while GLDM texture features from ADC maps were important for 1p/19q codeletion." (PMID 37697238, 2023). "In addition, CT and MRI metrics associated with TERT mutation in gliomas have also been researched for preoperative prediction." (PMID 37570630, 2023). "The univariate results showed that tumor grade, surgical resection range, preoperative KPS score, postoperative radiotherapy and chemotherapy, IDH1/2 gene and TERT promoter mutation were the influencing factors of postoperative survival of patients with glioma." (PMID 37250582, 2023). "TERT promoter mutations are frequently observed in gliomas with wild-type IDH." (PMID 37373295, 2023). "Univariate analysis showed that tumor WHO grade, resection range, preoperative Karnofsky performance status score, postoperative radiotherapy and chemotherapy, IDH1/2 gene and TERT promoter mutation influenced postoperative survival of patients with glioma (P<0.05)." (PMID 37250582, 2023). "Forty‐two percent of IDH‐mutant gliomas carry TERT promoter mutation." (PMID 36176070, 2023). "Targeting FOS in the FOS/GABP/mutant TERT cascade might be an effective therapeutic strategy for gliomas harboring TERT promoter mutations." (PMID 37372381, 2023).
glioma (continued). "Other groups have shown that glioma cases with gain of 7p, loss of 10q, and mutation in the TERT promoter biologically represent a different subtype, which is prognostically relevant and has clinical impact for proper risk stratification of patients and choice of treatment." (PMID 37973912, 2023). "In gliomas, TERT gene mutation is positively correlated with IDH mutation and 1p19q co-deletion, therefore it may be involved in early stage tumor development." (PMID 37372381, 2023). "According to updated 5th WHO classification of CNS tumors, some wildtype gliomas (with TERT promoter mutation or EGFR gene amplification or + 7/− 10 chromosome copy number changes), that were classified as °II and °III before are now considered as “molecular” glioblastoma." (PMID 36739296, 2023). "An indirect link to the inhibition of apoptosis in gliomas is the alternative lengthening of telomeres (ALT) due to mutations of the gene for telomerase reverse transcriptase (TERT) that lead to TERT overactivation, thereby preventing tumor cells from apoptosis." (PMID 37626776, 2023). "The panel includes several glioma-related genes and misses only the p-TERT mutation." (PMID 37908227, 2023). "IDH1/2 gene and TERT promoter mutations are more frequent in patients with human glioma." (PMID 37250582, 2023). "Univariate analysis showed that tumor WHO grade, resection range, preoperative KPS score, postoperative radiotherapy and chemotherapy, IDH1/2 gene mutation and TERT promoter mutation significantly affected the postoperative survival of patients with glioma (P<0.05), as shown in Table-II." (PMID 37250582, 2023). "It has been hypothesized that TERT promoter mutations enhance the neoplastic potential of tumors with low rates of self-renewal, such as low-grade gliomas." (PMID 36831683, 2023). "Of all TERT mutated gliomas, 27% showed EGFR amplifications." (PMID 35453544, 2022). "Over the last decade, isocitrate dehydrogenase (IDH) mutations, chromosome 1p/19q deletions, MGMT and TERT promoter methylations, and histone mutations have all served as glioma biomarkers; these markers play key roles in glioma classification and treatment decisions." (PMID 36579333, 2022). "Recent recommendations from the cIMPACT-NOW consortium suggest that EGFR amplification and combined chr7 gain and chr10 loss as well as TERT promoter mutation can be used to diagnose IDH wild type (WT) grade II/III gliomas that are likely to follow a more aggressive clinical disease course." (PMID 35211690, 2022). "Expression data and an association with shorter telomeres already strongly indicate the role of the TERT promoter mutations not only in glioma, but in many other cancer types, and future functional studies will aid in placing the TERT promoter mutations into the right context." (PMID 34558656, 2022). "Mutation statuses of IDH and TERT promoter have been used to classify gliomas in previous studies." (PMID 35495630, 2022). "Interestingly, the authors have validated 3 White-reported glioma risk loci in the Chinese population: rs2736100 (ORrandom-effect = 1.27; 5p15.33; TERT), rs498872 (ORfixed-effect = 1.25; 11q23.3; PHLDB1), and rs6010620 (ORfixed-effect = 1.29; 20q13.33; RTEL1)." (PMID 36350002, 2022). "TERT promoter mutation is a poor prognostic indicator in wt-IDH gliomas." (PMID 36505786, 2022). "Moreover, EGFR amplification was found to be present solely in IDH wildtype gliomas (26%) and TERT mutated gliomas (27%), occurring independently of MGMT promoter methylation status and being mutually exclusive with 1p/19q codeletion (LOH)." (PMID 35453544, 2022). "Therefore, the consequence of TERT-p mutation and its interaction with other molecular markers in glioma pathogenesis remain to be fully understood." (PMID 35495630, 2022).
glioma (continued). "Mutations of the promoter region of TERT have been suggested to be a key terminal event in the evolution of glioblastomas, but it has an intriguing property of being mutated also in oligodendrogliomas, which are mostly low-grade gliomas." (PMID 35558510, 2022). "By way of example, common polymorphisms near TERT, which are associated with longer telomeres, are the most common germline single-nucleotide variants associated with a wide variety of cancers, including melanoma and glioma (reviewed in 55, 66)." (PMID 35609925, 2022). "A study with MRS found that TERT-mutated tumors could have more necrosis, probably related to the high-grade profile that TERT mutations confer to low-grade gliomas." (PMID 35693015, 2022). "The frequency of TERT promoter mutations in gliomas increases with the increasing WHO grade." (PMID 35931979, 2022). "EGFR amplification is a phenomenon of IDH wildtype TERT mutated high-grade gliomas." (PMID 35453544, 2022). "In addition, to date, many results have been reported under the assumption that telomerase enzyme activity is equivalent to TERT expression or TERTp mutation in gliomas, but this paradigm has been challenged recently." (PMID 35953846, 2022). "We found that EGFR amplification is a phenomenon of IDH wildtype TERT mutated high-grade gliomas." (PMID 35453544, 2022). "In this study, CCL2, CCL5, CXCR4, MMP9, and CXCR2 expression was found to be high in TERTmut glioma from all samples and IDHwt subgroups with high levels of neutrophil infiltration, which indicated that N2 phenotype neutrophils were associated with TERT mutation." (PMID 33996815, 2021). "Similarly, MGMT promoter methylation and TERT promoter mutations, both well-known molecular markers correlated to drug-resistance in gliomas, were also found to be preserved in GBM primary cells but lost in grade II/III primary cells." (PMID 33981597, 2021). "Mutations in the promoter region of TERT may facilitate TERT expression and serve as a crucial onco-marker in gliomas, particularly in glioblastomas (GBMs)." (PMID 34422648, 2021). "TERT mutation may be a potential immune therapeutic target for optimizing treatment combinations and patient selection for glioma immunotherapy." (PMID 33996815, 2021). "Therefore, we considered that the TERT promoter status was associated with the immune response in glioma." (PMID 33996815, 2021). "However, in grade II/III gliomas, TERT promoter mutation serves as a favorable prognostic factor similar to IDH mutations." (PMID 33981597, 2021). "Gliomas with the TERT mutation had higher MVD compared with TERT wild-type in our study." (PMID 34814870, 2021). "Additionally, we also found this changing trend in 1p19q codeletion and TERT mutation gliomas, which seldom reported." (PMID 33777772, 2021). "Indeed, tumors harboring TERT-p mutation at high frequency, such as melanoma, thyroid papillary carcinoma, and glioma, are also well known for a high frequency of BRAF mutation." (PMID 33635430, 2021). "For TERT, it had been shown the promoter mutations were correlated with poor prognosis and shorter survival of patients with glioma, and some researches also identified that TERT promoter mutations was an independent prognostic factor in the other human cancer." (PMID 34114970, 2021). "In this study, we hereby propose that TERT mutation might be a molecular driver of the dysfunctional immune microenvironment in IDH-wt glioma." (PMID 33996815, 2021). "Moreover, TERT promoter mutations were observed in almost all gliomas with concurrent total 1p/19q loss and IDH1/2 mutations (98%)." (PMID 34638714, 2021).